EGFR (epidermal growth factor receptor)
Diseases named in the same sentence as EGFR in open-access papers (continued):
Sharing a sentence is not in itself a finding about the gene and the disease.
cancer (continued). "In this study, we have monitored early metabolic response to treatment with 213Bi-anti-EGFR-MAb in two different cancer cell lines in vitro via GC–MS-based analysis of 13C-glucose incorporation into amino acids." (PMID 33737524, 2021). "In addition to the involvement of soluble E-cadherin, this may be attributed to the high expression of EGFR in the cancer cells used in this study, potentially because overexpression of EGFR and its oncogenic mutations can lead to spontaneous dimerization of EGFR, resulting in receptor activation." (PMID 33641663, 2021). "Phosphatidic acid (PA) provides a druggable signaling pathway that can be used to promote EGFR endocytosis and arrest at recycling endosomes, with selective deleterious effects against several EGFR-dependent cancer cells." (PMID 34298835, 2021). "EGFR in cancer cells is overexpressed, thereby activating fibroblasts and myeloid cells via several molecules such as AREG." (PMID 34326696, 2021). "The HER2 receptor belongs to the epidermal growth factor receptor (EGFR/ErbB) family of receptor tyrosine kinases and represents one of the main oncogenes involved with aggressiveness and poor prognosis of cancers." (PMID 34830899, 2021). "The high heterogeneity of this type of cancer, on the other hand, restricts the survival advantage of patients undergoing EGFR-targeted treatment, indicating the need for more research into new prognosis-related molecular mechanisms." (PMID 34447695, 2021). "As indicated, most studies encapsulated additional therapeutic agents such as anti-Her-2-antobodies or anti-EGFR-antibodies, capable of targeting overexpressing cancer cells while simultaneously holding intrinsic tumoricidal power." (PMID 34835777, 2021). "While the roles of Pgrmc1 and the EGFR-mediated signaling pathway have been extensively studied in a variety of cancers, the role of Pgrmc1, its signaling pathway, and interaction with EGFR remain poorly understood in the context of HCC." (PMID 34069911, 2021). "For cancer driver mutations, most hypermutated PDAC patients carried EGFR mutations at a high frequency, which explains their poorer clinical response to immunotherapy." (PMID 34503126, 2021). "EGFR driver alterations are acquired in the early step of cancer progression and can be identified in most neoplastic cancer cells." (PMID 33953280, 2021). "A series of thieno[2,3-d]pyrimidine-based hydroxamic acid hybrids was designed and synthesised as multitarget anti-cancer agents, through incorporating the pharmacophore of EGFR, VEGFR2 into the inhibitory functionality of HDAC6." (PMID 34187263, 2021). "Other GPCR ligands such as LPA, prostaglandins, bradykinin, gastrin-releasing peptide (GRP), and bombesin (BN) can also transactivate EGFR to induce cancer proliferation, survival, and invasion." (PMID 33746610, 2021). "This was further investigated using an LDH endpoint cytotoxicity assay on cancer cell lines displaying a varying degree of EGFR expression." (PMID 33686177, 2021). "Previous work indicates that hr-HPV oncoproteins, when ectopically over-expressed experimentally or in cancer-derived cells, augment EGFR signaling." (PMID 33481911, 2021). "In order to easily penetrate the cells and increase the therapeutic intake, the micellar surface was modified by adding ligands (epidermal growth factor receptor, folate, etc.)that more quickly recognize the receptors expressed on the surface by cancer cells." (PMID 34683855, 2021). "Compared to the free erlotinib that causes cell arrest at the G1/S transition, the introduction of the gold moiety promoted a drastic modification of its bioactivity while keeping its selectivity towards EGFR-expressing cancer cells." (PMID 34070457, 2021).
cancer (continued). "Accordingly, targeting the EGFR with small-molecule inhibitors represents a promising strategy in cancer therapy." (PMID 34771085, 2021). "Epigallocatechin-3-gallate (EGCG), the main bioactive molecule in green tea, acts as a tyrosine kinase inhibitor toward cancer cells overexpressing EGFR (wild-type)." (PMID 34769263, 2021). "Basically, EWI‐2 depletion forces miR‐3934‐5p to be packaged into exosomes and transferred outside of cells, eventually acting as a bridge between different cancer cells and activating EGFR signaling." (PMID 33605506, 2021). "EGFR overexpression or mutation often correlate with drug resistance thereby presenting EGFR as a possible target in many malignant tumors." (PMID 33918106, 2021). "It is notable that PGRMC1 is able to activate intracellular Akt signaling in cancer through the epidermal growth factor receptor (EGFR) tyrosine kinase, the typical trafficking target for PGRMC1." (PMID 33767621, 2021). "They concluded that the conjugation strategy of binding AuNPs to EGFR antibody was an important factor that affected the effectiveness of cellular uptake and the active feature of AuNPs in cancer cells." (PMID 34322025, 2021). "Along with sustaining cell proliferation and conferring resistance to anti-cancer cytotoxic drugs, EGFR strongly promotes metastasis through a large collection of paracrine loops, each controlling a critical step of the metastasis cascade." (PMID 34206026, 2021). "Aberration of EGFR signal activation, transduction, duration and intensity can result in disruption of cancer cell homeostasis." (PMID 34298667, 2021). "EGFR is a major signal transducer of mitogens in cancer pathogenesis and progression upstream of mTOR and is an important target in anti-cancer therapies." (PMID 34361836, 2021). "Rasarfin also potently inhibits agonist-induced ERK1/2 signaling by GPCRs, and MAPK and Akt signaling by EGFR, as well as prevents cancer cell proliferation." (PMID 34344896, 2021). "SOCS5 is a potential negative regulator of EGFR, as has been demonstrated in both human cancer cells 25-26 and a Drosophila epithelial transformation model." (PMID 33758600, 2021). "All cancer cell lines except Caco-2 (3.4%) showed a high interaction level with ErbB2, as ErbB2 is another major interacting partner of EGFR in addition to EGFR itself." (PMID 33603128, 2021). "The search included all publications in which the miRNAs were connected to EGFR inhibitor treatment, erlotinib treatment in particular and cancer cells or bio fluid samples from cancer patients." (PMID 34012511, 2021). "For DEmiR target enrichments, numerous cancer-related pathways were shown, and EGFR-related pathway, “PI3K/Akt pathway”, was also enriched." (PMID 34646755, 2021). "Specific receptor blockers which inhibit the EGFR-induced signaling pathway can prevent cancer progression." (PMID 34943898, 2021). "Cetuximab can induce ADCC by binding to EGFR on cancer cells and CD16 receptor on natural killer (NK) cells and dendritic cells (DCs)." (PMID 35111681, 2021). "Another in vitro PTT study, which used 30 μg/mL concertation of anti-EGFR functionalised AuNRs in combination with a 808 nm laser at 2 W/cm2 power density for 5 min in MDA-MB-231 cancer cell, demonstrated around 76.5% of cancer cell death." (PMID 34683944, 2021). "We demonstrate in this MET-driven subset of EGFR TKI-refractory cancers that canonical EGFR downstream signaling was governed by MET, even in the presence of sustained mutant EGFR expression and activation." (PMID 34516823, 2021). "Here, we showed that the natural active compound in licorice, glycyrrhizin (GL), directly binds to heme-dimerized PGRMC1 to inhibit PGRMC1-mediated EGF receptor (EGFR) activation in cancer cells." (PMID 34209885, 2021). "On the other hand, EGFR is involved in regulating the proliferation and survival of many types of cancer cells." (PMID 34830108, 2021).
cancer (continued). "Phosphorylation is considered a key modification of BECN1, and several reports have demonstrated that EGF/EGFR signaling negatively regulates autophagy by directly binding to BECN1 in cancer cells." (PMID 34131122, 2021). "Accumulating evidence suggested that miR-138 regulated cancer cells proliferation by inhibiting target genes expression that was implicated in some pro-cancer signaling pathways, including insulin-like growth factor (IGF), EGFR, AKT and MAPK." (PMID 34340705, 2021). "Several studies demonstrated that the downstream PI3K/Akt, ERK, and JNK signaling pathways of EGFR were activated in cancer metastasis of HCC, and the inhibition of EGFR or its downstream signal pathway would inhibit cancer metastasis." (PMID 33688369, 2021). "US8946235B2 states 2-(2,4,5-substituted-anilino)pyrimidines, useful in treating a disease mediated by EGFR, for example, cancer." (PMID 34451807, 2021). "Antibodies have been targeted to EGFR to reduce the signaling for cancer cell growth and are used as therapeutic agents." (PMID 33670650, 2021). "The purpose was to explore possible mechanisms that affected the EGFR inhibitor response in cancers and provide novel targets for anti-EGFR inhibitor resistance." (PMID 34356665, 2021). "Based on previous studies, we have been interested in developing specific therapeutic agents and exploring their structure–activity relationship (SAR) for patients with cancers resistant to EGFR-TK inhibitors." (PMID 34681198, 2021). "Dysregulation of the EGF receptor (EGFR) signaling pathway is frequently met in human cancers, including CRC." (PMID 34638601, 2021). "Epidermal growth factor receptor (EGFR) is a proto-oncogene that is overexpressed in many human cancers, and is a potential therapeutic target." (PMID 34150374, 2021). "EGFR-specific TKIs induce wide-ranging IFN response program activation originating within the cancer cell." (PMID 34001994, 2021). "It is well known that activated EGFR pathways promote the proliferation and invasiveness activities of cancer cells." (PMID 34174844, 2021). "Although many EGFR antibodies and inhibitors, including cetuximab, afatinib, osimertinib, erlotinib and gefitinib, have been applied to cancer treatment." (PMID 34376189, 2021). "We earlier reported that the activation of cancer‐related receptors (e.g., epidermal growth factor receptor) and the expression of oncogenic K‐Ras can enhance macropinocytosis, resulting in enhanced cellular uptake of EVs." (PMID 33533170, 2021). "EGFR alterations in microgravity have also been reported by other authors investigating different cancer cell types." (PMID 34445479, 2021). "The mRNA expression profiles of LANCL2 and EGFR were investigated in 32 different cancers of TCGA database." (PMID 34461927, 2021). "In conclusion, resistant cancer cell-derived exosomes induced gemcitabine resistance via exosomal ANXA6, which was associated with the inhibition of EGFR ubiquitination and degradation." (PMID 34238922, 2021). "On the other hand, the proportions of patients with mutations in the epidermal growth factor receptor (EGFR), a family history of cancer and a poor prognosis differed among reports." (PMID 33767239, 2021). "EGFR can be transferred by cancer cell-derived exosomes to vascular endothelial cells (VECs) which enables VEGF to be secreted." (PMID 33855679, 2021). "Epidermal growth factor was discovered in 1962, and the first clues on the role of EGF/EGFR in cancer cell biology appeared in the 1980s." (PMID 34211836, 2021). "Cetuximab is a chimeric monoclonal antibody (mAb) that selectively binds to the epidermal growth factor receptor (EGFR), inhibiting its role in cancer-cell proliferation, resistance to apoptosis and metastasis." (PMID 34206707, 2021). "In general, PGRMC1 is also known to interact with EGFR and further activates intracellular Akt signaling in cancer." (PMID 34970218, 2021).
cancer (continued). "EGFR is one of the most ubiquitous cancer cell surface receptors and is overexpressed on skin, lung, colon, head and neck, breast, and oesophageal cancers." (PMID 34332294, 2021). "Starting with this notion, EGFR has been considered a very interesting target to treat diverse cancer types, including GBM." (PMID 34063168, 2021). "Several mechanisms have now been identified linking EGFR signaling to canonical pathways of NF-κB activation, mostly in the context of cancer cells." (PMID 35083168, 2021). "Numerous investigations have revealed that GPCRs, like PARs, are able to exploit EGFR as a downstream signaling partner for generating potent mitogenic signals contributing to cancer development and progression." (PMID 33093643, 2021). "Several other studies on the cutaneous adverse reactions in cancer patients under EGFR inhibitors were mentioned in depth throughout the article." (PMID 34362003, 2021). "Confocal imaging studies confirmed the enhanced uptake of 6-O-sulfated HS-tetrasaccharide by EGFR-overexpressed cancer cells, whereas their phosphate derivatives showed weak EGFR-mediated uptake rates." (PMID 34163672, 2021). "EGFR is a key receptor protein that is present on the surface of both normal cells and cancer cells." (PMID 33767988, 2021). "Epidermal growth factor receptor (EGFR) is a cancer-related gene and it also has been reported to be a potential biomarker of HPV infection." (PMID 34646755, 2021). "In the present study, we provided evidence for the first time that FGFC1 possessed selective anti-cancer activity against EGFR-mutant PC9 and H1975 NSCLC cells." (PMID 35126111, 2021). "Although patients with metastatic colorectal cancer (mCRC) exhibited a high efficacy to anti-EGFR antibodies such as cetuximab or panitumumab, drug resistance was also observed in cancer cells." (PMID 34884633, 2021). "PE38 binds to EGFR-expressing cancer cells due to the TGFα fragment present in the recombinant fusion protein." (PMID 33738260, 2021). "The resulting chimeric EGFR-targeting MrNV VLPs that we created exhibited great potential as nano-containers for targeted delivery of therapeutic compounds to cancer cells." (PMID 34400669, 2021). "To investigate the role of HOIP in EGFR signaling-mediated cancer development, we injected HOIP wild type or knockout A431 cells into the flanks of nude mice." (PMID 34769306, 2021). "The threshold level of EGFR for antitumor effects of panitumumab was found to be more than 17,000 receptors per cell in xenograft models using human cancer cells." (PMID 34207383, 2021). "Targeting OXPHOS restores the sensitivity of vemurafenib (v-Raf murine sarcoma viral oncogene homolog B (BRAF) inhibitor) - and gefitinib (Epidermal growth factor receptor (EGFR) inhibitor)-resistant cancer cells to the corresponding drugs." (PMID 33673109, 2021). "Accordingly, cell growth was suppressed by the depletion of AP-1 in a non-cancer cell line, ARPE-19, and a NSCLC-derived cancer cell line, H1975, which harbors activating EGFR mutations." (PMID 34799560, 2021). "Epidermal growth factor receptor (EGFR) is a transmembrane receptor tyrosine kinase that is overexpressed in various malignant tumors, including NSCLC." (PMID 34445110, 2021). "Another link with mitochondria in cancer cell metastasis is epidermal growth factor receptor (EGFR)." (PMID 33498743, 2021). "EGFR alterations are common in many malignant tumors such as lung, breast, stomach, and colorectal cancer and glioblastoma." (PMID 34578147, 2021). "SPINK1 overactivity resulted in progression and cancer spread via epidermal growth factor receptor in experimental mouse models." (PMID 33599076, 2021). "In the past decades, due to the advances of cancer genomics, a group of gene alterations is identified as driver gene mutations for LUAD, such as mutations in epidermal growth factor receptor (EGFR), c-MET, KRAS, anaplastic lymphoma kinase (ALK)." (PMID 33386920, 2021).
cancer (continued). "Apart from the extracellular domain, the juxtamembrane region of EGFR is targeted by peptides to reduce the EGFR signaling for cell growth in cancer cells." (PMID 33670650, 2021). "Direct current electric field (dcEF)-mediated epidermal growth factor receptor (EGFR) polarization and Ca2+ influx promote cancer cell electrotaxis." (PMID 36046433, 2021). "In cancer genomes, frequent substitutions at glycosylation sites are apparent in epidermal growth factor receptors and oncogenes EGFR and ERBB3, as well as PAPPA, a secreted protein involved in the activation of insulin-like growth factor pathways." (PMID 33834021, 2021). "Even its kinase activity is inhibited by lapatinib, EGFR still can confer survival signal in cancer cells." (PMID 34267653, 2021). "PE38 is a recombinant immunotoxin prepared as a conjugate between TGFα and a laboratory-engineered Pseudomonas exotoxin A. The PE38 immunotoxin is under investigation for EGFR-positive cancers, for example brain tumors." (PMID 33738260, 2021). "The expression of ZEB1 in cancer cells from NSCLC patients with acquired resistance to EGFR‐TKI has been previously investigated." (PMID 33764690, 2021). "For instance, if one of the previously identified NSCLC-associated genes, such as EGFR, ALK, ROS1, BRAF, RET, MET, or NTRK, is mutated in the patient’s cancer cells, targeted therapies has to be considered." (PMID 33845897, 2021). "Under threatening conditions for cancer cells, like the presence of EGFR inhibitors and apoptosis inducers, EGFR translocates in mitochondria and contributes to drug resistance." (PMID 34422883, 2021). "This concept is supported by alterations in the ability of cancer cells to migrate and proliferate due to derailed RTK trafficking and by EGFR/integrin recycling‐dependent regulation of cancer cell migration." (PMID 34086370, 2021). "These phosphorylated tyrosine residues are bound to several adapter proteins, the EGF/EGFR signaling pathway is activated, which plays a critical role in cancer cells proliferation." (PMID 32901097, 2021). "Of these, cetuximab, a chimeric mAb, and panitumumab, a human mAb, have been widely used in EGFR-expressing cancers." (PMID 34332294, 2021). "EGFR can be found on the cell membrane surface, and its expression is elevated in cancer, moderate in adenoma, and very decreased in normal epithelia." (PMID 34638601, 2021). "EGFR Tyrosine kinase inhibitors (TKI) bind to the tyrosine kinase domain in the epidermal growth factor receptor and undermine the EGFR function of cancer cell to cure the cancer." (PMID 35004854, 2021). "This manuscript presents an overview of the accumulated evidence on HER2- and HER3-targeting therapy, especially ADCs, and discussion of remaining issues for further improving these treatments in cancers resistant to EGFR inhibitors." (PMID 33801379, 2021). "The CTD2 data set had a total of 79 unique drugs with sensitivities across 351 cancer cell lines that involve 22 targets, such as EGFR, HDAC1, MTOR, MET, ERBB2, and BRAF." (PMID 33795761, 2021). "EGFR is one of four members of the ErbB family of receptor tyrosine kinases that have key roles in development and the progression of many cancers." (PMID 34054523, 2021). "This study identifies a path towards curing EGFR-expressing cancer cells using bi-functional liposomal nanoparticles simultaneously delivering cytotoxic effects of 188Re radioactivity and 5-FU chemotherapy." (PMID 33672989, 2021). "HAF binds to the recombinant extracellular domain of EGFR which is overexpressed in various cancers." (PMID 34502049, 2021). "In the present study, we revealed that exosomal ANXA6 derived from chemoresistant cancer cells induced gemcitabine resistance by inhibiting the ubiquitination and degradation of EGFR." (PMID 34238922, 2021).